TNF (tumor necrosis factor)
Diseases named in the same sentence as TNF in open-access papers (continued):
Sharing a sentence is not in itself a finding about the gene and the disease.
psoriasis (continued). "Since TNF-α is also considered to be the central cytokine in this autoimmune disease, it can give predictions of the exacerbation susceptibility of psoriasis." (PMID 35203707, 2022). "A TNF-α 238 G/A polymorphism was found to be significantly associated with a reduced risk of psoriasis in the general population." (PMID 36012327, 2022). "As with TNFα, IL-17A is associated with barrier tissue chronic inflammatory diseases including psoriasis and IBD, and drugs inhibiting IL-17A signaling are currently used to treat patients." (PMID 36591258, 2022). "Recent case reports have suggested that anti-tumor necrosis factor (TNF) agents are associated with an increased risk of developing psoriasis in patients with inflammatory bowel disease (IBD)." (PMID 35801760, 2022). "Cytokines implicated in psoriasis pathogenesis mainly IL-17, IL-23, TNF-α, IL-1, IL-22, IFN-α and IFN-γ are linked to JAK-STAT pathway." (PMID 35265634, 2022). "Nevertheless, we found two significant bins harboring five different genes associated with anti-TNF-induced PPP in patients with a different background other than psoriasis." (PMID 36143237, 2022). "In this study, we aimed to determine the association between anti-TNF treatment and psoriasis development in patients with IBD by conducting a meta-analysis of published studies." (PMID 35801760, 2022). "A previous study from our laboratory found five SNPs (rs11209026 in IL23R, rs10782001 in FBXL19, rs3087243 in CTLA4, rs651630 in SLC12A8, and rs1800453 in TAP1) associated with anti-TNF-induced paradoxical psoriasis reactions." (PMID 36143237, 2022). "A significant association between psoriasis and MS was detected after adjusting for variables of age, sex, PsA, and exposure of TNF-α agent." (PMID 35757712, 2022). "In the underlying mechanism of psoriasis, TNF-α or IL-23 are the upper stream cytokines, whereas IL-17 are the downstream cytokines." (PMID 35457278, 2022). "BT are particularly affected by targeting various genetic or immune mediators act in pathophysiology, like blocking the TNF-α, interleukins, which mainly cause inflammation or other manifestations of psoriasis." (PMID 34365780, 2022). "The same result was reached by a large-scale observational study that confirmed a reduction by 11.2% of CV event risk in psoriasis patients exposed to TNF-α inhibitors for 6 months compared to those who received phototherapy." (PMID 35686132, 2022). "Taken together, pathogenic mechanisms observed in psoriasis involve a number of different cytokines of the T cell immune response and TNFα signaling." (PMID 35812457, 2022). "TNF-857, 308, 238 (rs1799724, rs1800629, rs361525 respectively) polymorphisms have been linked to psoriatic susceptibility and anti-TNF responses in psoriasis and other inflammatory illnesses like Crohn's disease and ankylosing spondylitis." (PMID 35035485, 2022). "Given that chronic inflammation is a hallmark of psoriasis, we then perform an RT-PCR assay to determine the mRNA levels of IL-1β, IL-6, and TNF-α." (PMID 35351863, 2022). "Cultured primary keratinocytes treated with the ferroptotic inducer erastin had reduced viability and increased expression of a suite of psoriasis-associated cytokines (TNF-α, IL-6, IL-1α, IL-1β, IL-17, IL-22, and IL-23)." (PMID 35929827, 2022). "GWAS has been recently used to identify new genetic biomarkers associated with the differential response to anti-TNF agents, and only two studies were performed in psoriasis." (PMID 36059983, 2022). "CD84 is a known T cell activation marker, genetic variants of which have been associated with response in psoriasis to TNF blockade." (PMID 35958578, 2022). "This meta-analysis of published studies aimed to evaluate the association between anti-TNF treatment and psoriasis in patients with IBD." (PMID 35801760, 2022). "TNF-alpha inhibitors were the most frequently implicated drugs, and psoriasis was the most common condition for which the biologic drug was prescribed." (PMID 36615129, 2022).
psoriasis (continued). "Various amino acids, such as proline, arginine, glycine, threonine, and aspartate, were closely associated with after anti-TNF-α treatment in psoriasis patients." (PMID 33391503, 2021). "The FBXL19 rs10782001 (G > A, C) polymorphism was evaluated in a study of predictive biomarkers for the risk of developing toxicity and/or paradoxical psoriasis due to anti-TNF drugs in Spanish patients with moderate-to-severe psoriasis (n = 161)." (PMID 33921427, 2021). "For example, studies on psoriasis lesions showed that overexpression of IL-17 and TNF increase melanocyte number and cause a simultaneous decrease in pigmentation signaling." (PMID 33921371, 2021). "TNF-α inhibitors reduce the risk of cardiovascular events and improve the cardiovascular outcome in patients with psoriasis." (PMID 34803716, 2021). "TNF-α is secreted by T lymphocytes and plays a regulatory role in the pathogenic process during the development of psoriasis." (PMID 35056961, 2021). "The patients carrying the SLC12A8 rs651630-AA genotype showed a higher risk of developing paradoxical psoriasis during treatment with anti-TNF medication (OR = 0, CI95% = 0–0.06, p = 0.011)." (PMID 33921427, 2021). "It has been reported that an increased level of TNF-α was detected in the serum of patients with psoriasis, and its rising was associated with disease activity." (PMID 35056961, 2021). "Combination therapy of anti-TNF-α with other immunosuppressants is linked with a reduced risk of psoriasis." (PMID 33802483, 2021). "Many variant alleles of HLA-I and HLA-II genes have been described, and their association with the risk of developing psoriasis or relationship to response to biological therapy (anti-TNF and UTK) have been studied." (PMID 33921427, 2021). "More than 200 variants of the tumor necrosis factor (TNF) gene have been identified, four of which are the most extensively studied in psoriasis because of their relationship to its physiopathology." (PMID 34577605, 2021). "Specifically, polymorphisms of the CTLA4 (rs3087243), FBXL19 (rs10782001), SLC12A8 (rs651630), and TAP1 (rs1800453) genes have shown an association with susceptibility to developing toxicity and/or paradoxical psoriasis due to anti-TNF drugs." (PMID 34577605, 2021). "The SLC12A8 rs651630 (G > A) polymorphism was evaluated in a study of predictive biomarkers for the risk of developing toxicity and/or paradoxical psoriasis due to anti-TNF drugs in Spanish patients with moderate-to-severe psoriasis (n = 161)." (PMID 33921427, 2021). "A previous meta-analysis consisting of 2253 psoriasis patients and 1947 controls highlighted that TNF-α -308G/A polymorphism was significantly associated with decreased risk of psoriasis (GA versus GG: OR 0.67, 95%CI 0.57–0.78, p < 0.001)." (PMID 35126146, 2021). "Psoriasis-like keratinocytes were generated by treating human primary keratinocytes with the psoriasis-associated cytokines IL-17A, TNF-α and IL-22." (PMID 33801280, 2021). "In psoriasis, MCs can be activated by IL-1, causing inflammation and triggering a cytokine network including IL-33 and TNF cytokines." (PMID 34360845, 2021). "In our study, we analyzed an association between one of the VDR gene polymorphisms, level of TNF, IL-17, IL-23, vitamin D and psoriasis in the Polish population." (PMID 34208603, 2021). "Psoriasis is a complex disease, caused by an inflammatory cascade involving cytokines as TNFα, and the IL-17/IL-23 axis." (PMID 35024224, 2021). "The impact of polymorphisms in the IL23R gene on the response to anti-TNF drugs in biologic-naive patients diagnosed with moderate-to-severe psoriasis has been evaluated in a study with Spanish patients (n = 109)." (PMID 33921427, 2021). "We focused our efforts on genes involved in TNF and IL-17 signaling, as both pathways have previously been linked with the molecular pathophysiology of psoriasis and are targeted by (also here applied) available treatment options." (PMID 34746142, 2021).
psoriasis (continued). "Obesity and psoriasis have a common pathogenic mechanism involving the fat cells critical for the synthesis of the pro-inflammatory cytokines IL-6 and TNF-α." (PMID 34372872, 2021). "Local levels of cytokines associated with psoriasis, such as IL-17, IL-22, IL-6, and TNF-α, were also reduced after sGal-9 treatment." (PMID 34354596, 2021). "Specifically, TNF-α is a proinflammatory cytokine implicated in the pathogenesis of psoriasis that activates the NF-κB signaling pathway." (PMID 34884596, 2021). "The cytokines currently thought to be associated with psoriasis include tumor necrosis factor (TNF)-α, interleukin (IL)-17, and IL-23, but TNF-α is thought to be the cytokine with the greatest impact on the cardiovascular system." (PMID 34441936, 2021). "For this perspective we found studies demonstrating that psoriasis patients treated with IL-12/23 blockers showed a reduced risk for serious infection compared with those who received TNF or IL-17 inhibitors." (PMID 34242265, 2021). "Increased levels of 4-HNE and 4-HNE protein adducts have been observed in plasma and blood cells, as well as skin cells (keratinocytes and fibroblasts) of patients with psoriasis, causing higher expression of NF-kB and TNFα in blood cells." (PMID 33450863, 2021). "TNF-α, is the historic molecule investigated first as a pathogenic driver in psoriasis, it has demonstrated an indirect role in skin pathophysiology, promoting the effects of the IL-23/IL-17 axis." (PMID 34829740, 2021). "TNF-α levels are higher in psoriatics than in normal individuals, and the improvement is linked to the psoriasis area and severity index score." (PMID 34834393, 2021). "In this line, it becomes clear that the reduction or inhibition of key cytokines in the pathogenic mechanism of psoriasis (NF-κB, TNF-α, IL-1β, IL-23, and IL-17) plays an important role in the activity of the flavones." (PMID 34943117, 2021). "Keratinocytes and leukocytes both contribute to pathogenic inflammatory cycle in psoriasis with a central role of TNF/IL-23/IL-17 in chronic skin inflammation." (PMID 34298932, 2021). "We further estimated the cytokine secretion of skin fibroblasts and basal cells under TNF-α stimulation, a canonical signaling involved in psoriasis and indicated by our susceptibility gene loci analysis." (PMID 33958582, 2021). "TNF‐α is linked to a wide variety of autoimmune diseases, including RA, psoriasis, SLE, and diabetes." (PMID 31999357, 2021). "Subsequently, the impact of the FCGR3A-V158F and FCGR2A-H131R polymorphisms on anti-TNF response was assessed in a pilot study with biologic-naive Spanish patients diagnosed with moderate-to-severe psoriasis and treated with ADA, INF or ETN (n = 70)." (PMID 33921427, 2021). "The HLA-Cw*06 alleles (also known as HLA-C*06:02) have been shown to confer a high risk of suffering from psoriasis, but its association with response to anti-TNF drugs and cytokine inhibitors is contradictory." (PMID 33921427, 2021). "Various studies have demonstrated that the risk of cardiovascular comorbidities in psoriasis patients reduced after treatment with TNF-α inhibitors." (PMID 34803716, 2021). "Among various molecules associated with psoriasis, tumor necrosis factor (TNF)-α, IL-23, IL-17 and IL-22 are important regulators of psoriasis." (PMID 34134787, 2021). "She consulted the rheumatology department for consideration of 30 mg/day PSL, but was bio-switched to the IL-6 inhibitor sarilumab (SAR) in June Y+2 due to the high risk of infection and a history of synovitis and psoriasis induced by TNF inhibitors." (PMID 35008766, 2021). "These are the same pro-inflammatory cytokines that underlie the immune mechanisms of psoriasis, including TNF-alpha, IL-6, and C-reactive protein." (PMID 34441010, 2021). "The exacerbation or new onset of psoriasis-like skin lesions is a common adverse event associated with TNF-α inhibitors 10,11." (PMID 33859756, 2021).
psoriasis (continued). "Consistently, we found elevated levels of serum TNFα, one important pathogenic mediator in psoriasis." (PMID 34660638, 2021). "The use of methotrexate and anti-TNF treatment reduces the risk of comorbidities and is conducive to improvement of psoriasis, but anti-TNF-a antibody therapy is associated with an increase in adiposity." (PMID 34372872, 2021). "For RA and psoriasis, treatment with a biologic drug that targets TNF correspondingly is associated with decreased risk for AD." (PMID 32203525, 2020). "A recent study has shown that TNF-α blockers were also effective in decreasing depressive symptoms associated with psoriasis." (PMID 33364982, 2020). "Pathogenesis of psoriasis and its comorbidities share both genetic predisposition and inflammatory pathways, which include the TNFα and the IL-23/IL-17 pathways." (PMID 32161545, 2020). "One explanation is adipose tissue in obese persons produce inflammatory adipocytokines, such as leptin, resistin, and TNFα, leading genetically predisposed patients to develop psoriasis." (PMID 32276410, 2020). "Psoriasis patients receiving TNF-α inhibitors had a lower major cardiovascular event risk compared to those receiving MTX (Kaplan–Meier rates: 1.45% vs. 4.09%: p < 0.01." (PMID 32121574, 2020). "As TNF inhibitors such as infliximab, etanercept, and adalimumab have been widely used in the management of psoriasis, the association between TNF inhibitors and the risk of tuberculosis has been analyzed." (PMID 32987907, 2020). "Of particular, psoriasis patients that received tumor necrosis factor (TNF) inhibitor showed a decreased carotid intima-media thickness, suggesting the protective effect of TNF inhibitors on CV risk in patients with psoriasis." (PMID 32987907, 2020). "We now confirm that induction of S100-alarmins in an imiquimod-induced murine model of psoriasis-like skin inflammation was associated with an increased expression of interleukin (IL)-1α, IL-6, IL-17A, or TNFα." (PMID 33643287, 2020). "In patients with moderate-to-severe psoriasis, treatment with apremilast was associated with significant reductions in plasma levels of interleukin (IL)-17F, IL-17A, IL-22, and TNF-α." (PMID 33178709, 2020). "Psoriasis represents another autoimmune inflammatory disease associated with increased serum levels of TNF-α." (PMID 33053859, 2020). "More specifically, the replacement of guanine with adenine in position-238 is linked to a higher production of TNFα, and consequently to a higher risk of psoriasis in the Caucasian population." (PMID 33007857, 2020). "In psoriasis, systemic vascular inflammation is caused by interleukin (IL) -6, IL-12, IL-23, tumor necrosis factor (TNF) -α production and oxidative stress, which induce thrombosis in the vessels and lipid dysregulation." (PMID 33322823, 2020). "Recent studies have shown that psoriasis is associated with migraine, as the endothelial dysfunction caused by increased TNF leads to vascular impairment." (PMID 33322823, 2020). "Patients diagnosed with a systemic inflammatory disease are at increased risk for developing AD, while TNF blocking agents were associated with decreased risk for co-morbid AD in real-world patients diagnosed with RA or psoriasis." (PMID 32203525, 2020). "Although the causes of psoriasis are unclear, mouse models and biological treatment of humans show that underlying immunological mechanisms are dependent on the tumor necrosis factor (TNF)/interleukin (IL)-23/IL-17 axis." (PMID 32486022, 2020). "The identification of genetic biomarkers correlating with an adverse response to anti‐TNF‐α therapy will be fundamental to predict the risk of developing paradoxical psoriasis." (PMID 31577850, 2020). "In this sense, it has been recently described an EV-associated miRNAs signature increased in serum of psoriasis patients that returns to normal levels after successful treatment with anti-TNF-alpha." (PMID 32630692, 2020).
psoriasis (continued). "Research have showed that activated Th1 and Th17 T cells (CD4+ T cells), CD8+ T cells, as well as increased levels of cytokines such as IL-17, IL-23, TNF-α and IL-27, have been directly implicated in psoriasis immunopathogenesis." (PMID 32848737, 2020). "Therapeutic success by specific biologics points to the pathogenic role of the tumor necrosis factor-α (TNF-α) axis and the interleukin (IL)-23/IL-17A axis in psoriasis." (PMID 31936670, 2020). "In contrast to these anti-inflammatory functions, TNF antagonists interestingly can also cause the appearance of psoriasis-like lesions in 5–10% of treated patients, named as ‘paradoxical psoriasis’." (PMID 31295952, 2019). "Another study has also shown that the addition of a cytokine cocktail (IL-1α, TNF-α, IL-6) leads to the expression of proteins associated with psoriasis such as SKALP, hBD-2, keratin-16, TNF-α and IL-8." (PMID 30987186, 2019). "Cytokines such as tumor necrosis factor alpha (TNFα) and interleukin 6 (IL-6) are directly implicated in the pathology of psoriasis and are targets for some highly effective treatments." (PMID 30703100, 2019). "Inhibitors of tumor necrosis factor in psoriasis showed a significant reduction in the risk of myocardial infarction compared with topical agents." (PMID 31480330, 2019). "In one part of the study, patients with psoriasis of a mean age of 47 years, with low cardiovascular risk, and treatment with anti-TNF and anti-IL7 were included." (PMID 31275060, 2019). "Activated Th1 and Th17 T cells (CD4+ T cells) and CD8+ T cells, as well as increased levels of cytokines such as IL-17, IL-23, TNF-α and IL-27, have been directly implicated in psoriasis immunopathogenesis." (PMID 31130981, 2019). "We also demonstrate that our IL-19 assay has similar applicability for psoriasis patients treated with tumor necrosis factor (TNF)α inhibitors such as etanercept, or Janus associated kinase (JAK) 1/2 inhibitors such as baricitinib." (PMID 30914699, 2019). "It has been reported in several studies that TNF inhibitors are associated with an increased risk of SI in patients with psoriasis and in patients with PsA or RA." (PMID 31799498, 2019). "Several studies have shown that control of these pathologies favours good evolution of psoriasis and concurrently that treatment with methotrexate and anti-TNF would reduce the risk of these comorbidities." (PMID 31275060, 2019). "We here demonstrate unique effects of IL-36 in epidermal KCs and functional associations between IL-36 and other cytokines validated as psoriasis drug targets (i.e., TNF, IL-17A, and IL-23)." (PMID 29434599, 2018). "Rs361525 polymorphism, also known as TNF-238, is a SNP in the TNF-α gene which has been linked to a wide variety of conditions: breast cancer, Graft-versus-host disease, psoriasis, diabetes, glaucoma, lymphoma and many others." (PMID 29696068, 2018). "We show that IL-36γ induces the production of psoriasis-associated cytokines from macrophages (IL-23 and TNFα) and that this response is enhanced in macrophages from psoriasis patients." (PMID 29535706, 2018). "In conclusion, this study confirms that two SNPs in the IL12B and TNF genes are associated with susceptibility to psoriasis in Danish patients with moderate-to-severe psoriasis." (PMID 29389950, 2018). "The TNF −238AA genotype and TNF −238A allele were found to be a marker of systemic lupus erythematosus and psoriasis." (PMID 30627222, 2018). "Nowadays, the pathogenic role of the TNF/IL-23/TH17 axis in psoriasis is well-known and numerous biologics targeting the different cytokines of this pro-inflammatory pathway are widely used in the clinic." (PMID 30555460, 2018). "Elevated levels of TNF-α, a key player of angiogenesis, and other cytokines including IL-1 and IL-6 in psoriasis are associated with type 2 diabetes." (PMID 29904118, 2018).